APOE (apolipoprotein E)
Diseases named in the same sentence as APOE in open-access papers (continued):
Sharing a sentence is not in itself a finding about the gene and the disease.
neurodegenerative disease (continued). "ApoE isoforms modulate the risk for a variety of vascular and neurodegenerative diseases; thus, APOE genotyping is crucial for predicting disease risk and designing individualized therapy based on APOE genotype." (PMID 26754117, 2016). "In view of the importance of APOE genotyping in predicting individual risk for a variety of vascular and neurodegenerative diseases, we have developed a rapid and cost-effective method for analyzing APOE polymorphism." (PMID 26754117, 2016). "Other proteins such as prion protein (PRNP), neurogenic locus notch homolog protein 3 (NOTCH3), apolipoprotein E (APOE) associated with neurodegenerative diseases were also enriched in CSF exosomes." (PMID 26861304, 2016). "APOE gene polymorphism modulates the risk for a variety of vascular and neurodegenerative diseases; thus, APOE genotyping is crucial for predicting disease risk and designing individualized therapy based on APOE genotype." (PMID 26754117, 2016). "Polymorphism in APOE gene is a risk factor for various neurodegenerative diseases, and the protein has been shown in the lesions of these disorders." (PMID 25071560, 2014). "Genes involved in neurodegenerative diseases, kinesin light chain 1 and apolipoprotein E, showed association with age-related cataract." (PMID 19649315, 2009). "The findings are consistent with known neurobiological function of APOE ε4, including both increased risk of neurodegenerative disease and reduced synaptic integrity in older age." (PMID 17974013, 2007). "The observations offer an explanation for the stratification of clinical outcome with APOE seen in several degenerative diseases or brain that are associated with activated innate immune response." (PMID 16934151, 2006). "Growing evidence, however, indicates that APOE ε4 carriage may also have a role in other age-associated neurodegenerative diseases." (PMID 40665049, 2025). "Given that APOE ε4 carriers across neurodegenerative diseases share major underlying systemic proteomic changes, we sought to better understand additional drivers that may be disease specific." (PMID 40665049, 2025). "It remains unclear, however, why APOE ε4 is more strongly associated with AD in terms of prevalence despite exhibiting systemic biological effects across neurodegenerative diseases." (PMID 40665049, 2025). "While APOE genotyping can inform treatment decisions, it also raises ethical concerns due to the broader implications of disclosing genetic risk information for neurodegenerative diseases." (PMID 40761402, 2025). "The APOE ε4 isoform increases the risk for neurodegenerative diseases." (PMID 40301749, 2025). "Given that APOE ε4 is linked to a shared molecular phenotype across neurodegenerative diseases, this hypothesis is consistent with current understanding." (PMID 40665049, 2025). "This enabled us to ask whether the APOE ε4-associated proteomic signature is shared across multiple neurodegenerative diseases." (PMID 40665049, 2025). "Interestingly, the APOE E4 allele is a known risk factor for AD, suggesting a mechanistic difference between neurodegenerative diseases affecting the eye and brain." (PMID 40778276, 2025). "Future prospective studies should incorporate more detailed environmental and behavioral measures, such as physical activity, diet, sleep, substance use and immunization history, to better characterize modifiers of neurodegenerative disease risk in APOE ε4 carriers." (PMID 40665049, 2025). "The neurodegenerative disease and biomedical research communities have made significant progress in understanding the structure, function, associated pathologies, and clinical impact of apoE." (PMID 39031528, 2024). "This is of particular interest as the basal ganglia are the brain structures with the highest iron concentrations in healthy brains, and abnormally increased basal ganglia iron levels are often found in neurodegenerative diseases, for which the APOE ε4 allele is a major risk factor." (PMID 35951362, 2022).
neurodegenerative disease (continued). "In addition to the inflammatory signaling pathways, proteins/chemicals/toxins associated with neurodegenerative diseases (beta-amyloid, N-methyl-4-phenylpyridium, and Apolipoprotein E (APOE)) were inferred to be upregulated in astrocytes and microglia." (PMID 35273209, 2022). "We therefore hypothesize that a peripheral ε4 phenotype, despite the inability of apoE to enter the CNS is related to the increased risk of developing neurodegenerative diseases." (PMID 35418601, 2022). "Summary of APOE locus genetic association with neurodegenerative disease across global populations." (PMID 36337698, 2022). "Several protein groups associated with aging and neurodegenerative diseases including apolipoprotein E (ApoE), S100B, Sod1, Sod2, huntingtin (Htt), macrophage migration inhibitory factor (Mif), α-Synuclein (Snca) were modulated by either drug treatment or the behavioural training per se." (PMID 34907284, 2021). "Furthermore, APOE genotype has been shown to be associated with the progression or poor clinical outcomes of other neurological or neurodegenerative diseases." (PMID 34453582, 2021). "It has been proposed that the presence of an ApoE ε4 allele could increase AD co-pathology across neurodegenerative diseases." (PMID 33466854, 2021). "Alternatively, the risk of sporadic neurodegenerative diseases might be increased through various susceptibility genes, such as apolipoprotein E (APOE), which might be perhaps also negatively influencing PrP aggregation." (PMID 32375593, 2020). "Additionally, we list sex-by-genotype interactions identified across neurodegenerative diseases, proposing APOE variants as a shared etiology for sex differences in the manifestation of these diseases." (PMID 32859588, 2020). "In addition, accumulating evidence suggests that APOE variants drive sex-specific vulnerability to neurodegenerative diseases other than LOAD (reviewed in Box 2)." (PMID 32859588, 2020). "Moreover, despite universal occurred NVU dysfunction, only a subgroup of TBI victims develop late-onset neurodegenerative diseases, indicating other factors should be taken into consideration, such as genetic susceptibility (e.g., APOE genotyping)." (PMID 32581697, 2020). "The ApoE ε4 allele may also play a role in early-onset AD, delaying the onset of symptoms, and in other neurodegenerative diseases, where APOE ε4 status is a risk factor for co-pathology and poor evolution." (PMID 32733362, 2020). "APOE is regulated by estrogen, progesterone and testosterone, raising the possibility that hormone-APOE interactions underlie the sex differences in susceptibility to neurodegenerative disease and, furthermore, that the role of APOE in LOAD pathogenesis is sex specific." (PMID 32859588, 2020). "AD is a progressive neurodegenerative disease induced by multiple factors, such as apolipoprotein E genetic risk variants, excessive levels of phosphorylated tau protein, immunoinflammatory responses and Aβ deposition, all of which contribute to AD pathogenesis through the Aβ-dependent pathway." (PMID 30740049, 2019). "There are ApoE isoform-dependent differences in the anti-inflammatory role in neurodegenerative diseases and such differences might in part explain the differential risk for AD caused by ApoE isoforms." (PMID 30909239, 2019). "Thus, the ApoE knock out mouse model should help us to understanding the underlying biological mechanisms of neurodegenerative disease and the role of cholesterol metabolism in cognition." (PMID 29510495, 2018). "The ApoE knockout mice might therefore be an appropriate model for studying the underlying mechanisms involved in behavioral changes caused by neurodegenerative diseases as well as for evaluating new therapies for these pathologies." (PMID 29510495, 2018).
neurodegenerative disease (continued). "However, in consideration of the recognised protective effect of APOE2 against AD and other neurodegenerative diseases, we calculated in detail APOE-allele specific ORs considering the E3/E3 as reference class." (PMID 29518107, 2018). "Therefore, our APOE genotyping method can be used for assessing the risk for a variety of vascular and neurodegenerative diseases that have been reported to be associated with APOE polymorphism." (PMID 26754117, 2016). "Additionally, the ε4 allele of APOE was found to be a risk factor for other neurodegenerative diseases including cerebral amyloid angiopathy (CAA), dementia with Lewy bodies and multiple sclerosis." (PMID 26754117, 2016). "The purpose of this review is to elucidate the potential role of ApoE polymorphisms in personalized medicine, with a specific focus on neurodegenerative diseases, by giving an overview of its influence on disease risk assessment, diagnosis, prognosis, and therapy." (PMID 25071563, 2014). "The association of ApoE with other neurodegenerative diseases is less clear." (PMID 25071563, 2014). "Subtle APOE-4-associated changes on cortical structure may also become less consistently detectable in patients with a neurodegenerative disease." (PMID 24228185, 2013). "We hypothesized that differential expression of apoC-I depending on APOE genotype could represent a novel mechanism for APOE genotype-associated risk for neurodegenerative diseases." (PMID 22883744, 2012). "Although all APOE ε4 carriers have a systemic immune-related proteome signature, we find that the relationships between proteins within this signature are uniquely associated with demographic, lifestyle, and clinical variables in a neurodegenerative disease-specific manner." (PMID 40665049, 2025). "Neuron and glia specific ABCA1 deficiency leads to poor lipidation of apoE, and significant decrease of cholesterol level, decrease of apoE level in brain, leading to the pathological injuries that are tightly associated with degenerative diseases neurodegenerative diseases." (PMID 35296367, 2022). "In addition, epidemiology studies will continue to determine whether genetic risk factors for neurodegenerative diseases, for example, variations in apolipoprotein E (APOE) or COMT, can predict risks of developing chemobrain in cancer survivors." (PMID 32346964, 2020). "Interestingly, expression of several non-ISG, non-immune genes was reduced in uninfected Lrrk2 KO BMDMs, including ApoE, which has been repeatedly linked to inflammatory and neurodegenerative diseases, and Ldhb, a critical metabolic gene involved in post-glycolytic energy production." (PMID 32057291, 2020). "APOE may moderate the relationship between frailty and memory by promoting more widespread neuropathology, particularly in the deeper, medial regions associated with memory before the onset of neurodegenerative disease." (PMID 31221191, 2019). "Thus, the mechanism behind the increased risk of female ApoE ε4 carriers of developing cardiovascular and/or neurodegenerative diseases might involve serum levels of IGF-1 or other aspects of IIS activity reflected by these levels." (PMID 21418511, 2011). "Serum neurodegenerative disease biomarkers, brain amyloid beta (Aβ), APOE, and tau, learning and memory, hippocampal mitochondrial function and proteomics data were collected." (PMID 42100472, 2026). "Apolipoprotein E (APOE) ε4 is known to influence the spread of pathological protein in several neurodegenerative diseases, raising the possibility that it also modulates the pathological distribution of TDP-43 inclusions in ALS." (PMID 42141160, 2026). "Our analyses revealed unique, neurodegenerative disease-specific significant relationships with APOE." (PMID 40665049, 2025). "In our study, proteins within the APOE ε4 signature were differentially correlated with demographic, lifestyle, and clinical variables, in a neurodegenerative disease-specific manner." (PMID 40665049, 2025).
neurodegenerative disease (continued). "Our results demonstrate that voluntary exercise effectively mitigates cardiac dysfunction induced by a high-fat diet in mice with humanized APOE genotypes, which model different degrees of CVD and neurodegenerative disease risk." (PMID 41417779, 2025). "Structural alterations in ApoE’s receptor-binding domain, such as those resulting from the L122P or L107P variants, may disrupt its interaction network, potentially impairing Aβ homeostasis and diminishing neuroprotective capacity, thereby contributing to neurodegenerative disease mechanisms." (PMID 40892789, 2025). "Despite persistent challenges, ongoing ApoE research instills optimism for pioneering therapeutic interventions capable of attenuating or arresting the progression of neurodegenerative diseases." (PMID 39944166, 2025). "An unexpected finding of our study was that plasma neurofilament light (NEFL) levels were lower in APOE ε4 carriers across neurodegenerative diseases, despite NEFL’s growing recognition as a biomarker of neurodegeneration." (PMID 40665049, 2025). "It has been reported that APOE is involved in dysfunctional microglia in neurodegenerative diseases." (PMID 40338234, 2025). "The work presented at the conference and through this section suggests these domains enable the spectrum of interactions and functions that make apoE a critical component of various neurodegenerative diseases." (PMID 39031528, 2024). "The apolipoprotein E (APOε) is a component of lipoprotein complexes that has a multifunctional role in the homeostasis of cholesterol, neurobiology, and in neurodegenerative diseases." (PMID 39125677, 2024). "APOE is well known for its role in lipid transport, cholesterol metabolism, and maintaining neuronal integrity, particularly in the context of neurodegenerative diseases." (PMID 39727961, 2024). "Among them, Apolipoprotein E (APOE) is a protein, vital to lipid metabolism and is involved in pathophysiology of several degenerative disorders such as neurodegenerative diseases." (PMID 38126810, 2024). "The APOE ε4 has been identified as the most significant genetic risk factor associated with AD11 and other neurodegenerative diseases, including frontotemporal lobar dementia (FTLD), Lewy body dementia (LBD), and other amyloid‐beta (Aβ) and tau pathologies." (PMID 39031528, 2024). "APOE protein is mainly expressed by glial cells including astrocytes, microglia, and oligodendrocytes, and is involved in the pathogenesis of neurodegenerative diseases." (PMID 37446179, 2023). "APOE therapy has been a recent topic of interest as a novel strategy to target multiple neurodegenerative diseases including AD and CAA." (PMID 36922879, 2023). "Perhaps more importantly, this review outlines what we can learn from the interactome of ApoE and amyloid proteins; that is the need to see both ApoE and amyloid proteins as a basis to understand neurodegenerative diseases." (PMID 36817952, 2023). "Despite the importance of sleep and the prevalence of sleep disruptions observed across multiple neurodegenerative diseases, especially AD, little is known about the interactions between sleep, APOE genotype, and AD pathology." (PMID 37279069, 2023). "ApoE is a lipid-transport protein known to control the inflammatory characteristics of activated microglia in various neurodegenerative diseases." (PMID 38139244, 2023). "Our results suggested APOE ε4 has a large impact on the calculated damage from multiple neurodegenerative diseases, especially on ANIMAL test." (PMID 37926851, 2023). "Genetic, model system, and neuropathology studies have clearly established Aβ, tau and APOE as disease hallmarks, biomarkers and therapeutic targets in AD and other neurodegenerative diseases." (PMID 36609403, 2023). "It is well known that APOE is an important gene in the occurrence and progression of neurodegenerative diseases." (PMID 37633927, 2023).
neurodegenerative disease (continued). "Nonetheless, such areas of investigation are still increasing, since ApoE function in neurodegenerative diseases, particularly AD, cannot be uniquely explained by ApoE effects in lipid metabolism." (PMID 38132357, 2023). "It suggests that ApoE dysregulation plays a key role in the transition of homeostatic microglia to DAM in neurodegenerative diseases." (PMID 35693341, 2022). "Other lipoproteins, such as ApoE, have been related to aging and neurodegenerative diseases, while lipid metabolism has strong links to neurotrophic disorders and correlates with symptoms in PD patients." (PMID 36414996, 2022). "In this review, we discuss the evolutionary selection and differences in the genetic architecture of two important loci in neurodegenerative diseases, 17q21.31 and APOE, among diverse global populations." (PMID 36337698, 2022). "In this section, we are exploring the importance of the APOE genotype in neurodegenerative diseases other than AD." (PMID 36153580, 2022). "It was demonstrated that saturated lipids contained in APOE lipoparticles mediate astrocyte-induced toxicity which kills neurons in neurodegenerative diseases." (PMID 35562955, 2022). "BBB dysfunction and breakdown is observed across many neurodegenerative diseases, including AD, with a dependency on APOE isoform." (PMID 36167428, 2022). "Nevertheless, there is still much to investigate and learn from APOE physiology and its implication in the context of neurodegenerative diseases." (PMID 36153580, 2022). "The main focus of this review is the role of APOE, and its isoforms, during neuroinflammation observed in neurodegenerative diseases, with particular attention to its role in neuroinflammation." (PMID 36153580, 2022). "These modules and clusters harbor known neurodegenerative disease genes including APOE, PLCG2, and BIN1." (PMID 35388616, 2022). "The APOE genotype is also related to the severity of other proteinopathies and neurodegenerative diseases characterized by overt neuroinflammation." (PMID 36153580, 2022). "Further studies taking into account the cellular sexual dimorphism will be of great value to further unravel the interaction between sex and the APOE genotype in neurodegenerative diseases, particularly in AD." (PMID 36153580, 2022). "ApoE controls phagocytic and inflammatory characteristics of microglia in neurodegenerative diseases." (PMID 34565486, 2021). "Apolipoprotein E (APOE) is a multifunctional protein with central roles in lipid metabolism, neurobiology, and neurodegenerative diseases." (PMID 32083135, 2020). "APOE therefore provides a genetic link between sleep and neurodegenerative disease, adding to the validity of this relationship." (PMID 33212927, 2020). "Study of genetically modified mice has contributed to our understanding of the susceptibility to AD and other neurodegenerative diseases conferred by mutations or variants in APP, APOE, and related genes." (PMID 32580938, 2020). "The aim of the study was to investigate if the concentrations of total apoE and the specific apoE isoforms in cerebrospinal fluid (CSF) differ between various neurodegenerative diseases and control individuals, as well as among the APOE genotypes." (PMID 32054532, 2020). "Many of these properties, that differ among the apoE isoforms, contribute to the protective functions of the brain apoE and apoE-containing particles, with respect to neurodegenerative diseases, similarly to what occurs for plasma HDL in CVD." (PMID 33287338, 2020). "Here, we review the literature on APOE, with a focus on its understudied neurobiological functions and the sex-specificity of its pathogenic effect in LOAD and other neurodegenerative diseases." (PMID 32859588, 2020). "The involvement of APOE in such a diverse array of functions adds layers of complexity to understanding its biological function in the brain and in neurodegenerative diseases." (PMID 32859588, 2020).